PPARD (peroxisome proliferator activated receptor delta)
Diseases named in the same sentence as PPARD in open-access papers (continued):
Sharing a sentence is not in itself a finding about the gene and the disease.
tumor (continued). "Treatment with the selective PPARδ agonist GW501516 markedly accelerated mammary carcinogenesis, particularly in MMTV-PDK1 mice, and the reduction in tumor latency correlated with a metabolic gene expression and metabolomic signature that differed from wild-type animals." (PMID 21297860, 2011). "However, maintaining animals on a diet containing the selective and potent PPARδ agonist, GW501516, immediately following DMBA, resulted in a dramatic acceleration of tumor formation." (PMID 21297860, 2011). "Therefore, we conclude that PPARD's activation on DVL1 leads to repressing PPARG's activity, and this gives clues for tumour repressor PPARG's inactivation and leads to cancer progression into the HR stage." (PMID 19640296, 2009). "Knockout of PPARδ in host tissues but not in tumor cells reducedtumor growth by impairing angiogenesis." (PMID 18551186, 2008). "Indeed, downregulation of PPARD reduced vitamin D receptor (VDR) expression and subsequently mitigated its inhibitory effect on the SOX2 promoter, thus promoting SOX2 expression and resulting in tumor growth and drug resistance of colorectal CSCs." (PMID 41148824, 2025). "Together, these data demonstrate that the metabolic regulator PPARδ is responsible for transcriptional and functional changes concomitant with EMT induction upon direct activation with chemical agonists or in response to starvation and tumor microenvironmental signals." (PMID 40607925, 2025). "In this study, we report that PPARδ is highly expressed in IL-10+ Bregs with a predominant surface phenotype of CD19+CD24hiIgDlo/−CD38lo or CD19+CD24hiIgDlo/−CD38hi, which present in naïve mice and can be induced by tumor formation and agonistic anti-CD40 mAb." (PMID 37291146, 2023). "Furthermore, KAT2A and PPARD showed different expression levels based on the tumor stage, while TCF7L2 expression showed no significant change between different tumor grades." (PMID 36476410, 2022). "Moreover, according to the C1-C6 immune subtypes previously identified by investigators, we classified tumor samples by representative immune signatures and examined the RNA-seq level of PPARA, PPARD, PPARG, PPARGC1A, and PPARGC1B from C1 to C6, which were all seen to have differential expressions." (PMID 33029111, 2020). "TMEM108 and C3orf47 were positively correlated with tumor grade and eight genes, including LAD1, TIF1, FGF11, carbonic anhydrase 12 (CA12), G protein subunit α15 (GNA15), junction plakoglobin (JUP), plakophilin 1 (PKP1) and PPARD, were negatively correlated with the tumor grade of ESCC patients." (PMID 28904855, 2017). "Furthermore, decreased PPARδ activity cannot be explained by reduced prostacyclin production since these effects are observed in tumor cell lines irrespective of their level of COX-2 expression and also after treatment with the non-COX-inhibitory sulindac sulfone." (PMID 23875171, 2013). "In addition, PPARδ agonist GW7042, which is almost identical to GW501516 in structure, potency, and specificity, was inactive in inducing gene expression in PPARδ knockout mice, suggesting that the tumor promoting effects of GW501516 and GW7042 are not due to off-target effects." (PMID 21318167, 2010). "PGE2 treatment did not increase intestinal adenoma burden in Min mice lacking PPARδ, concluding that PPARδ is a focal point ofcross-talk between the prostaglandin and Wnt signaling pathways, which resultsin a shift from cell death to cell survival, leading to increased tumor growth." (PMID 18528523, 2008). "In summary, due to the fact that we did not confirm the mutual correlation between miRNA-17 and PPARδ neither in the tumour tissue margins nor in NSCLC, we consider miR-17 and PPARδ as two independent molecular factors." (PMID 34921177, 2021). "The mRNA levels for several critical components of the pathway (BIRC5, CD44, FZD7, c-MET, MMP7, c-MYC, NOTCH1, PPARD, and VEGF) were significantly increased (DASL signal intensity) in TN tumor samples as compared to non-TN tumor samples." (PMID 24143235, 2013).
tumor (continued). "Compared to naïve mouse B cells, increased PPARδ expression was observed in B cells from tumor-bearing mice treated with Rat IgG but not with GSK, and this tumor-induced PPARδ upregulation in B cells was further elevated in mice treated with FGK but not with FGK plus GSK." (PMID 37291146, 2023). "The observed decreased PPARδ expression in NSCLC and its increased level in adjacent normal lung tissue may indicate its putative role as tumour suppressor gene." (PMID 34921177, 2021).
cancer (179 papers, 2006 to 2025). A tumor composed of atypical neoplastic, often pleomorphic cells that invade other tissues. "If so, studies to determine the role of PPARδ in cancer-associated fibroblast formation and function would be of interest." (PMID 39195246, 2024). "Glucose deprivation is known to cause oxidative stress in cancer cells, and PPARδ has been shown to fortify antioxidant defense." (PMID 33808242, 2021). "PPARδ is also associated with cancer by promoting chronic inflammation through increasing cyclooxygenase-2 (COX-2) expression and prostaglandin E2 production, leading to an increase in proinflammatory cytokine concentrations." (PMID 35010191, 2021). "PPARδ, a nuclear transcriptional receptor, is multifunctional, as it participates in glucose and lipid metabolism, inflammation, as well as cancer-associated biological processes, including EMT; its expression is upregulated in lung cancer." (PMID 33637678, 2021). "This molecular cross-talk between Wnt signaling and PPARδ has been implicated in many metabolic syndromes, such as obesity, diabetes and the development of cancer." (PMID 33673357, 2021). "Prolonged high-fat diet (HFD) in mice activates PPAR-δ (peroxisome proliferator-activated receptor-delta) in ISCs to upregulate a subset of β-catenin target genes associated with cancer cell stemness." (PMID 34887764, 2021). "In a series of studies, we found that the high PPARδ expression was linked to longer survival in patients with primary cancers, and PPARδ suppressed the proliferation and facilitated the differentiation of CRC cells." (PMID 34712608, 2021). "Some studies indicate that activating PPARδ causes increased cell proliferation in several different types of cells, including endothelial cells, keratinocytes, and cancer cells." (PMID 23607100, 2013). "Themost striking results were provided by a study demonstrating that in PPARδ deficient (Ppard−/−) mice, both Min mutants and those with chemically induced cancers, colon polyp formationwas significantly greater in those nullizygous for PPARδ." (PMID 18483618, 2008). "Further microscopy analysis, as indicated in the Materials and Methods, revealed that this association between PPARδ expression and malignant morphological features was a common rule in the majority of cancer samples tested." (PMID 16969348, 2006). "During the course of this study, we found that the cancer cells with cytoplasmic accumulation of PPARδ often exhibited morphological features associated with a highly malignant phenotype." (PMID 16969348, 2006). "As BCL3 and PPARD are known to be associated with NF-κB and have functional roles in cell adhesion, inflammation, proliferation, and cancer progression, they could be key modulators in the pathological changes at sites of tissue injury." (PMID 35406434, 2022). "Furthermore, increased FABP5 is associated with various cancers including skin cancer, by promoting the activation of PPARδ and the upregulation of its oncogenic target genes." (PMID 34298981, 2021). "In addition, previous reports have listed cancer development and increased cardiac risk among the side effects of PPARδ, AMPK, and PGC-1α stimulation." (PMID 32099540, 2020). "Finally, the fact thatPPARδ agonists may be used for other indicationsraises the concern of unintended consequences of such modulation of PPARδ, whichmay have a direct effect on the patient's risk of colon and perhaps other cancers." (PMID 18528523, 2008). "PPARD is overexpressed in various cancers, including breast, colon, lung, and head and neck cancers, and is regulated by oncogenic pathways such as k-Ras, Wnt, and Src." (PMID 39922804, 2025). "The enhanced invasiveness of cancer cells following PPARδ activation by GW0742 was reversed by MYC knockdown or PGC1A overexpression, suggesting that an elevated MYC/PGC1A ratio is essential for invasion." (PMID 40607925, 2025).
cancer (continued). "PPARD’s significant regulatory functions make it a promising yet complex target for therapeutic intervention in cancer and metabolic disorders." (PMID 39922804, 2025). "PPARδ is ubiquitously expressed in skin, adipose tissue, enterocytes, muscles, the heart, immune cells, and various types of cancer." (PMID 39451206, 2024). "PGE2 stimulates the occurrence and progression of various cancers by activating membrane receptors EP and nuclear receptor PPARδ in target cells." (PMID 38764576, 2024). "The expression of PPARδ can be observed in various parts of the human body and its expression levels vary in different types of cancer, including colorectal, gastric, and prostate cancer." (PMID 39156976, 2024). "We observed that PPARA and PPARG genes were upregulated in most para-cancer samples, while PPARD was upregulated in cancer tissues." (PMID 38529307, 2024). "Studies have reported the activation/suppression of PPARβ and PPARδ expression in various cancer cell models have resulted in the modulation of CRC." (PMID 38372868, 2024). "PPARD is one of the three main isotypes of peroxisome proliferator-activated receptors (PPARs), which has been widely studied in cancer." (PMID 38212774, 2024). "The activation of PPARδ by specific ligands can promote inflammation and cancer growth in certain tissue types." (PMID 37645246, 2023). "Conversely, silencing PPARδ inhibited this process, and in addition, PPARδ promoted chemoresistance in cancer cells, which was alleviated by PPARδ antagonists." (PMID 37251321, 2023). "PPARD downregulation and deletion have proved to suppress cancer cell metastasis in various cancer models in vivo." (PMID 37347737, 2023). "Disruption of PPARD expression in cancer cells suppresses the development and metastasis of mammary, pancreatic, and colon cancer and melanoma." (PMID 35163565, 2022). "Another analysis from the Pan-Cancer Atlas public database, using TCGA data, also showed that PPARδ expression was positively correlated with CCL2 expression." (PMID 35562376, 2022). "Nevertheless, PPARD is upregulated in many cancers, including breast, colon, lung, and head and neck cancers." (PMID 35163565, 2022). "The upregulation of PPARD (peroxisome proliferator-activated receptor–δ) as a nuclear transcriptional receptor has been reported in various cancers by regulating metastasis." (PMID 36476410, 2022). "Simultaneously, the cancer cell growth and expression of PPARδ (energy-producing promotor) was strongly inhibited by NSAIDs, enhancing the pro-apoptotic and anti-proliferative effects, particularly in MCF7POX-KO cells." (PMID 35409177, 2022). "Activated Wnt/β-catenin signaling increases the expression of CyclinD1, c-Myc, and PPARδ during embryonic development as well as during the progression of cancer." (PMID 33673357, 2021). "The emerging role of PPARδ has been reported during the pre-implantation period of embryonic development, cancer, and several metabolic disorders in response to β-catenin/TCF4 signaling." (PMID 33673357, 2021). "Previously, PPARδ was detected mainly in the cytoplasm of epithelial cells, and its expression was increased in cancer tissues compared to normal mucosa." (PMID 34712608, 2021). "Topical treatment with PPARδ agonists or antagonists should be critically evaluated because data on the role of PPARδ in cancer is controversial." (PMID 34298981, 2021). "Genes such as ECM, ITGA, FAK, PI3K, and PKB/Akt are involved in cancer pathways which were identified by RNA-seq, and PPARδ was identified by iTRAQ." (PMID 32140061, 2020). "PPARδ reportedly reduces the oxidative stress of cancer cells and enhances the survival signaling response." (PMID 29929789, 2018). "Endogenous or synthetic ligands can activate PPARδ resulting in inflammation and cancer depending on the specific ligands and tissue types." (PMID 28948004, 2017).
cancer (continued). "It has been well characterized that PPARD plays a pivotal role in lipid metabolisms, embryonic development, inflammatory response, wound healing and cancer in human and mice." (PMID 24058710, 2013). "It seems unlikelythat the discrepancy in PPARδ effects is due to species differences as mostof the cancer studies were done using mouse tissues." (PMID 19266055, 2009). "Non-agonist bound PPARδ has been shown to repress PPAR Response Element, PPRE, signalling and several lines of evidence point to the importance of PPARδ repressive actions in both cardiovascular and cancer biology." (PMID 19756148, 2009). "PPARδ stimulates fatty acid oxidation in heart andskeletal muscle, and plays a role in cell differentiation, placentaldevelopment, cancer, wound repair, and atherosclerosis." (PMID 18528523, 2008). "The chemopreventive NO-donating NSAIDs (NO-NSAIDs; NSAIDs with an NO-releasing moiety) modulate PPARδ and offer the opportunity to revisit the controversial role of PPARδ in carcinogenesis (several papers report that PPARδ either promotes or inhibits cancer)." (PMID 18528523, 2008). "There have been both significant work on andsignificant excitement about a potential role of PPARδ in cancer." (PMID 18528523, 2008). "NSAIDs downregulate PPARδ andreduce eicosanoid-mediated inflammation, and induce apoptosis incolon cancer cells, in contradistinction to the anti-inflammatoryeffects elicited by PPARγ agonists in colitis." (PMID 18566686, 2008). "PPARδ is highly expressed incolorectal cancer cells, and somatic cell knockout ofPPARδ reduced tumorigenicity in nude mice." (PMID 18566686, 2008). "This review summarizes the pharmacology of NO-NSAIDs, PPARδ cancer biology, and the relationship between the two." (PMID 18528523, 2008). "In epithelialovarian cancer cells, aspirin suppressed PPARδ function and cell growth byinhibiting ERK1/2." (PMID 18528523, 2008). "PPARδ is a downstream target of β-catenin/T cell factor-4, which is central incolon cancer pathogenesis and regulates other cancer-promoting genes like c-mycand cyclin D1." (PMID 18551186, 2008). "The cancer specimens were divided into two groups (high expression: n=15 (46.9%) and low expression: n=17 (53.1%)) based on the mean value of a cytoplasmic PPARδ score of 160 (see Materials and Methods regarding score determination)." (PMID 16969348, 2006). "In cancer tissues, the PPARδ protein was accumulated only in those cancer cells with highly malignant morphology, as represented by a large-sized nucleus, round-shaped nucleus, and presence of clear nucleoli." (PMID 16969348, 2006). "The differences in cytoplasmic PPARδ expression between adenomatous polyps and cancers were significant (P<0.0001)." (PMID 16969348, 2006). "More than half of the cancer tissues exhibited nuclear expression at less than 10%, whereas a considerable number of the cancer tissues showed cytoplasmic PPARδ expression." (PMID 16969348, 2006). "On the other hand, all the carcinoma tissues expressed the PPARδ protein to various extents, in the cytoplasm and/or nucleus." (PMID 16969348, 2006). "Importantly, we found costaining of PPARδ and the hypoxia marker HIF1α in specific groups of cancer cells heavily surrounded by stromal cells, further reinforcing a direct link between both pathways." (PMID 40607925, 2025). "Identifying the external signals, such as hormones, nutrients, or stress conditions, and the intracellular mediators that influence PPARD activity could provide deeper insights into its role in cancer and other diseases." (PMID 39922804, 2025). "In contrast, in cancer cells, PPARD may enhance AKT signaling to support proliferative and survival pathways, potentially due to different regulatory mechanisms or cofactors." (PMID 39922804, 2025). "Furthermore, glycolytic metabolism via the “Warburg effect” aids cancer cell survival in hypoxia by increasing PPARD and activating the AKT pathway." (PMID 39922804, 2025).